INS (insulin)
Diseases named in the same sentence as INS in open-access papers (continued):
Sharing a sentence is not in itself a finding about the gene and the disease.
Insulin resistance (continued). "In this study, most patients with WFS1-DM required insulin treatment and lacked the clinical features of insulin resistance, and the serum C-peptide level in carriers with rare and predicted deleterious variants was lower than that in the EOD group without rare variants." (PMID 37277527, 2023). "However, in an insulin resistance state, insulin secreted in response to hyperglycemia is neither able to stimulate glucose uptake in peripheral tissues (including adipose tissue), nor inhibit glucose production in the liver." (PMID 36979669, 2023). "In addition, the quantitative insulin-sensitivity check (QUICKI) was also determined by log transforming values of fasting glucose and the fasting insulin level with a cut-off of <0.33 for insulin resistance." (PMID 37375611, 2023). "Moreover, fasting insulin or insulin resistance measured via homeostatic model assessment of insulin resistance (HOMA-IR) was not significantly different between groups." (PMID 37561578, 2023). "Serum glucose and insulin levels, together with HOMA-IR index, were sustainably (p < 0.05) increased, while the serum 25 (OH)VitD level was decreased (p < 0.05) significantly in the NAFLD group compared the control group, suggesting disorders of glucose metabolism and a state of insulin resistance." (PMID 37261280, 2023). "In addition, the insulin tolerance test and mechanism of anti-inflammatory action can be analyzed in the future in order to elucidate how MLCT can produce anti-inflammatory activity under the condition of reducing insulin resistance." (PMID 36677779, 2023). "However, they also showed that the mice had an impaired insulin-secretion capacity rather than insulin resistance (on HFD)." (PMID 35208200, 2022). "In the late phase, within 4 weeks, improved insulin resistance was maintained after 4 weeks of D-LED PBM based on HOMA-IR and increased expression of insulin in IHC of the pancreas after 4 weeks of D-LED PBM as multifactorial effects may potentiate reductions in the serum glucose level." (PMID 36359885, 2022). "We speculate that in obese, non-diabetic individuals, insulin resistance is overcome by increased endogenous insulin secretion, making their net insulin action in the liver able to suppress MBL production." (PMID 36618347, 2022). "The previous study showed the improvement of insulin resistance without changing insulin levels, the authors described that these findings might be results of improvement of glucose toxicity." (PMID 35672759, 2022). "Moreover, controls and patients with peritoneal sepsis showed comparable values for HbA1c as an indicator for chronic glycemic status whereas both insulin resistant and septic patients had increased HOMA-IR, reflecting more acute insulin resistance in these groups." (PMID 35017615, 2022). "Our results suggest that the consumption of white HSC aqueous extract has a preventive effect on the development of obesity-induced insulin resistance, which may be related to decreased circulating FFA, which are well known to disrupt the insulin signaling cascade." (PMID 36554419, 2022). "However, in the absence of insulin or peripheral insulin resistance, GLUT4 remains intracellular within storage compartments (i.e., in muscle and fat cells) and alters glucose transport from the extracellular milieu into the cell which leads to hyperglycemia." (PMID 36556443, 2022). "Our findings did not support any relationship between miR-150 and markers of insulin resistance such as insulin, adiponectin, or FGF21, but showed that miR-150 might be an important regulator in the cholesterol and triglyceride metabolisms." (PMID 35498403, 2022). "Moreover, insulin tolerance tests demonstrated that βHET males were not protected from insulin resistance, as the βKO were." (PMID 34823065, 2022).
Insulin resistance (continued). "Finally, a study investigating central insulin resistance in clinical AD samples as well as in two different animal models of AD similarly revealed significant elevations in hippocampal pSer IRS-1, further supporting the presence of reduced insulin signaling." (PMID 36009470, 2022). "Thus, some indices are based on fasting plasma concentrations of glucose and insulin to substitute the fasting insulin level, such as the homeostasis model of insulin resistance (HOMA-IR), the quantitative insulin sensitivity check index (QUICKI) and the fasting insulin resistance index (FIRI)." (PMID 36568072, 2022). "In addition, differences between HFpEF and HFrEF in insulin resistance in non-diabetic patients who underwent a short insulin sensitivity test have been reported." (PMID 36547453, 2022). "However, selective deletion of EGFR in peripheral insulin-sensitive tissues, hepatocytes, skeletal muscle or adipocytes, failed to alter the onset of obesity and the insulin resistance." (PMID 35948530, 2022). "Fourth, we did not measure homeostatic model assessment-insulin resistance, fasting insulin, genetic factors, adipocytokines, unreported medication use, sympathetic activity, or autonomic imbalance, and therefore their possible confounding effects cannot be ruled out." (PMID 36361436, 2022). "Furthermore, mice lacking a functional vitamin D receptor show impaired insulin secretory capacity together with insulin resistance." (PMID 35406129, 2022). "To date, several precipitating factors potentially contributing to the development of SGLT2-i-induced DKA in T1D have been identified, which were a lower BMI, features of insulin resistance, disproportionate insulin reductions, and non-adherence to following sick day rules." (PMID 35745754, 2022). "The results of the present study showed a significant decrease in insulin, glucose, and HOMA-IR levels and a significant increase in QUICKI values in the EX group, suggesting that continuous participation in the aqua exercise had a positive effect on insulin resistance." (PMID 36295873, 2022). "However, recent experiments within our group suggest weight cycling does not worsen peripheral insulin resistance compared to obese animals, but rather impairs pancreatic insulin secretion." (PMID 36713396, 2022). "As a consequence, these tissues slowly develop resistance to the normal response to insulin (insulin resistance, IR), and pancreatic β-cells are stimulated to produce higher amounts of insulin to compensate for this systemic resistance and maintain normal glycaemia (<100 mg/dL)." (PMID 36079821, 2022). "Moreover, recent review articles reported that insulin does not alter ANGPTL8 levels in the circulation and that the association of ANGPTL8 with insulin resistance and HbA1c in non-diabetic subjects seems contentious." (PMID 35736472, 2022). "However, the relationship of circulating sphingolipids to insulin resistance is not absolute, as insulin-sensitizing treatments do not always change plasma sphingolipid content." (PMID 36030929, 2022). "Protection from insulin resistance was also displayed by rodents lacking the NT receptor NTSR3, which is directly implicated in the modulation of the glucose transporter GLUT4, one of the major regulators of insulin sensitivity in adipose tissue." (PMID 34455471, 2022). "Assuming that children with obesity develop a certain grade of insulin resistance, which is proven with elevated insulin levels in their blood, we can conclude that increased BCM and FFM along with FM could be the consequence of insulin’s anabolic function." (PMID 35626780, 2022). "However, in the CANDLE trial, no data on other insulin resistance indices were assessed with gold-standard methods, such as the hyperinsulinemic-euglycemic clamp test, the Matsuda-DeFronzo index, and adipose insulin resistance index." (PMID 35941584, 2022).
Insulin resistance (continued). "T1DM is due to an autoimmune disease where individuals have low insulin levels and thus cannot adequately regulate their blood glucose levels, whereas T2DM is due to insulin resistance, where the body does not use the insulin produced as well as it should therefore lead to high blood glucose levels." (PMID 35236427, 2022). "Moreover, as the major sources of white AT (WAT), the gonadal WAT (gWAT) secretes excessive exosomal miR-222 to promote insulin resistance in the skeletal muscle of high fat diet (HFD)-fed obese mode mice by suppressing its direct target gene, IRS1, an important regulator of insulin signaling." (PMID 36293266, 2022). "To determine if cellular senescence contributes to insulin resistance in hepatocytes, we treated IHH cells with the senescence-inducing drugs for 5 days, and measured the phosphorylation of key proteins of the insulin signaling pathway after acute insulin stimulation." (PMID 36072934, 2022). "However, the ICR at any plasma insulin concentration was not different between the Ob-T2D group and the other obese groups and was lower in the participants with obesity and insulin resistance than in the lean participants." (PMID 34905513, 2022). "Subgroup analysis 2: effect of insulin resistance on insulin kinetics, independent of adiposity." (PMID 34905513, 2022). "According to changes in normal pregnancy, insulin resistance occurs due to decreased glucose uptake and increased insulin secretion, and mainly GDM occurs in women whose pancreas does not function sufficiently to compensate for the insulin resistance caused by pregnancy." (PMID 34993347, 2022). "Insulin resistance means that insulin does not play its normal role in target organs, such as the liver, skeletal muscle, central nervous system, and adipose tissue, despite the presence of insulin in the blood." (PMID 35625542, 2022). "Insulin resistance, assessed by means of euglycemic clamps, has been found to be inversely correlated to skin sodium content in HD patients, suggesting that tissue sodium interacts with insulin pathways independent of uremic toxin levels." (PMID 37675006, 2022). "Increased body weight and adipose tissue may also lead to insulin resistance, and thus the lack of measurements of insulin and/or glucose levels of the animals may be considered a major limitation of our study." (PMID 35206342, 2022). "However, insulin resistance and peripheral, hepatic, and adipose tissue insulin sensitivity were not affected by the study’s anthocyanin-rich blueberry." (PMID 36355516, 2022). "As insulin resistance and fatty liver index (but not insulin secretion) correlated with changes in body fat and glycemia, we hypothesized that an insulin-resistant NAFLD might not be an independent risk factor." (PMID 36432409, 2022). "However, in insulin resistance states, insulin fails to suppress the release, which results in enhanced lipolysis and increased fatty acid flux to the non-esterified fatty acid plasma pool." (PMID 35565913, 2022). "Plasma insulin levels were significantly increased on the HFD diet as compared to the chow diet at t = 24 (10.6-fold, p < 0.001), while glucose levels remained similar, resulting in a significantly higher insulin resistance on the HFD (10.3-fold increase in HOMA-IR at t = 24, p < 0.001)." (PMID 35897797, 2022). "Insulin resistance is commonly defined by absent or inadequate response to insulin." (PMID 35884888, 2022). "Although, increase in adipocyte size has been positively correlated with insulin resistance, there is no direct evidence suggesting that adipocyte hypertrophy could alone diminish insulin responsiveness." (PMID 35963433, 2022). "In addition, intraperitoneal glucose tolerance test (IPGTT), homeostatic model assessment of insulin resistance (HOMA-IR), immunohistochemical staining for insulin in pancreatic islets, arterial blood pressure and 24-h urine protein (24hUP) excretion were performed at PND60." (PMID 36109770, 2022).
Insulin resistance (continued). "Thus, it is hypothezysed that insulin resistance could also be determined by sorting of GLUT4 into different vesicle compartments, or with alterations in distal sections of insulin signaling." (PMID 35651975, 2022). "Moreover, Japanese individuals are thought to have less β-cell mass and be less obese, which results in reduced insulin secretion without severe insulin resistance compared to Caucasian subjects." (PMID 36331940, 2022). "Thus, the relative hyperinsulinemia observed in insulin-resistant individuals with obesity, T2DM, and prediabetes would favor accrual of bone mass, although the effect may be modified by the severity of insulin resistance and ambient adipocytokines." (PMID 36686435, 2022). "We only measured FPG and HbA1c, not OGTT and insulin, so we could not determine whether participants’ glucose tolerance was impaired or in an insulin resistance state." (PMID 36364842, 2022). "The treatment of PPH was also found to regulate the insulin signaling in our study, which is consistent with a previous study reporting that the intragastric administration of PPH upregulated the gene expressions of IRS1 and IRS2 in the liver of diabetic mice, and reduced insulin resistance." (PMID 36011893, 2022). "The results indicate that the correction of NAD+ depletion in DRG may be sufficient to prevent DPN but does not significantly affect glucose tolerance, insulin levels, or insulin resistance." (PMID 35563288, 2022). "The absence of AKT phosphorylation in HLCs in Diff, a signal of insulin resistance development, may be related to the chronic exposure to high insulin concentrations (1.72 μM), as previously reported." (PMID 36714559, 2022). "On the other hand, via GPR75, RANTES/CCL5 stimulates insulin secretion from β-cell lines and mouse and human pancreatic islets in vitro, and improves glucose tolerance in lean mice and a mouse model of hyperglycaemia and insulin resistance without changing insulin sensitivity." (PMID 35628332, 2022). "Group 2 included patients with low insulin secretion function but without high insulin resistance." (PMID 35672344, 2022). "Moreover, insulin resistance in connection with hyperinsulinemia induces the accumulation of amyloid-β due to the lack of available insulin-degrading enzymes (IDEs)." (PMID 36232867, 2022). "Taken together, these data imply that HFD mice lacking integrin α2β1 have improved insulin sensitivity, suggesting that integrin α2β1 may play a role in the development of insulin resistance." (PMID 36054466, 2022). "Insulin resistance (IR) is stated as diminished insulin action regardless of hyperinsulinemia." (PMID 36111327, 2022). "The ECM involvement in obesity‐induced insulin resistance may be explained by the evidence that ECM remodelling contributes to increased collagen formation, a process responsible for generating a physical barrier for insulin diffusion and glucose transport." (PMID 36054466, 2022). "However, since PBEH acted as a moderate acetylcholinesterase inhibitor, it did not suppress insulin secretion and decreased insulin resistance." (PMID 35328781, 2022). "Our study suggests that WC might be more appropriate than BMI for identifying insulin resistance in late adolescence when considering specific insulin resistance markers that do not consider insulin, such as TG/HDL and TyG." (PMID 36079745, 2022). "The increased serum adiponectin levels observed in aged HFD male mice could be a compensatory mechanism to prevent insulin resistance, which was not sufficient to avoid the deterioration of systemic insulin sensitivity." (PMID 36615734, 2022). "Conversely, Cori treatment remarkably inhibited HFD-induced increase of fasting blood glucose and insulin concentrations, and strongly reversed the HOMA-IR value (decreased by 1.54 in HCR-L group and 2.23 in HCR-H group), exerting its ameliorating effects against insulin resistance." (PMID 36071929, 2022).
Insulin resistance (continued). "Hence, we chose 20 μM dosage to determine if autophagy inhibition per se can induce insulin resistance; it did not influence insulin-stimulated Akt phosphorylation in 3T3-L." (PMID 35990905, 2022). "A study suggested that Asians might have a lower ability to secrete insulin, and insulin resistance is possibly not the driver of T2DM in Asians." (PMID 36530401, 2022). "CVD risk may be related to increased insulin resistance in patients with NAFLD and a long T2DM duration or use of insulin, although we could not evaluate the insulin levels." (PMID 35740267, 2022). "However, when the increased insulin production fails to compensate for the insulin resistance, hyperglycemia ensues, leading to T2D." (PMID 36247456, 2022). "The change in TGs is somewhat reminiscent of the well-described absence of dyslipidemia in patients with monogenic severe insulin resistance due to biallelic or monoallelic INSR mutations, so again this does not preclude the INSR LOF variants being associated with reduced insulin sensitivity." (PMID 34875679, 2022). "Previous studies have demonstrated that insulin resistance in PAH is not owing to an increased secretion of insulin by the pancreas, but due to the disordered lipid metabolism which may incur inflammation via oxidized LDL-mediated vascular injury." (PMID 35865003, 2022). "Overall, the results of the present study suggest that the risk factors clustering in the metabolic syndrome acting independently of impairment of whole-body insulin sensitivity can aggravate myocardial insulin resistance in subjects with type 2 diabetes without cardiovascular disease." (PMID 35845046, 2022). "Fasting BG and insulin, and homeostasis model assessment of insulin resistance (HOMA-IR) at 16 h after fasting were not different between CANA-treated mice during the 4-week ad libitum feeding and during the 4-week pair-feeding, relative to vehicle-treated mice." (PMID 35048967, 2022). "However, HOMA2 insulin sensitivity and insulin resistance were not significantly different for the 3-Screen positive patients compared to 3-Screen negative patients." (PMID 34533636, 2022). "Therefore, SHP2 has rather a negative role in insulin-evoked PI3K signaling in vitro that contributes to insulin resistance." (PMID 36140242, 2022). "However, in subjects with insulin resistance, β-cells have no choice but to produce and secrete larger amounts of insulin, which finally leads to β-cell overwork." (PMID 35453568, 2022). "Adipose tissue is also an ectopic site for production of insulin and development of insulin resistance; however, in this study, we did not measure insulin stimulated FDG uptake or ascertain the changes in the expression levels of various GLUTs in different organs." (PMID 35883660, 2022). "Intra-muscular lipids may build when the rate of β-oxidation outpaces the rate of fatty acid absorption, which may have negative consequences for the insulin action, which imparts insulin resistance." (PMID 36290804, 2022). "Since supraphysiological doses of CCK stimulate pancreatic insulin secretion, higher levels of circulating CCK induced by chronic palmitate treatment could be a compensatory response to insulin resistance in the prediabetic condition, which leads to hyperinsulinemia." (PMID 35887100, 2022). "A possible explanation could be a compensatory response that regulates the expression of EXOC6/6B in β-cell or reflects that the diabetic donors suffer from insulin resistance rather than insulin secretion." (PMID 35336762, 2022). "Moreover, women with GDM have a greater reduction in insulin sensitivity and an increase in insulin resistance, and their insulin secretion is not sufficient to maintain euglycemia, which leads to glucose intolerance and GDM." (PMID 34302684, 2022). "Plasma NfL levels were not correlated with fasting insulin and insulin resistance." (PMID 35795150, 2022).